SELPLG (selectin P ligand)
Description:
A SLe(x)-type proteoglycan, which through high affinity, calcium-dependent interactions with E-, P- and L-selectins, mediates rapid rolling of leukocytes over vascular surfaces during the initial steps in inflammation. Critical for the initial leukocyte capture. (Microbial infection) Acts as a receptor for enterovirus 71.
Synonyms: PSGL-1; CD162; CLA; PSGL1
Tractability: Antibody: a drug acting on it is in phase 2 or 3 trials; its Gene Ontology location is reachable by antibodies, with high confidence; UniProt predicts a signal peptide or a membrane-spanning region. PROTAC: ubiquitination databases record sites on it; its protein half-life has been measured.
Target class: Adhesion
Gene: Protein-coding gene on chromosome 12 (108,620,413 to 108,633,894, reverse strand). Ensembl gene ENSG00000110876.
Subcellular location: Membrane
Subcellular location (Human Protein Atlas): Vesicles
Pathways (Reactome):
Hemostasis: Cell surface interactions at the vascular wall
Gene Ontology:
Molecular function: protein binding; receptor ligand activity; signaling receptor binding
Biological process: cellular response to interleukin-6; leukocyte migration; leukocyte tethering or rolling; cell adhesion; leukocyte adhesive activation; signal transduction
Cellular component: plasma membrane; plasma membrane raft; uropod; membrane
Genetic constraint (gnomAD): Loss-of-function variants: 4 observed, 2.32 expected, observed/expected ratio (o/e) 1.72, 90% interval 0.7 to 1.94. That is too few expected variants to judge how well the gene tolerates losing a copy. Missense variants: 478 observed, 544.44 expected, observed/expected ratio (o/e) 0.88, 90% interval 0.81 to 0.95. Synonymous variants: 230 observed, 230.55 expected, observed/expected ratio (o/e) 1, 90% interval 0.89 to 1.11.
Homologues: Orthologues: chimpanzee SELPLG (97% identical), macaque SELPLG (86% identical), guinea pig Selplg (50% identical), dog SELPLG (49% identical), mouse Selplg (47% identical), rat Selplg (45% identical).
Diseases named in the same sentence as SELPLG in open-access papers:
SELPLG is named in the same sentence as 185 diseases in open-access papers, as found by Europe PMC text mining. Sharing a sentence is not in itself a finding about the gene and the disease. The quoted sentences say what the papers report.
atherosclerosis (24 papers, 2011 to 2025). A disease characterized by the build-up of fatty material and calcium deposition in the arterial wall resulting in partial or complete occlusion of the arterial lumen. "The SELPLG gene polymorphism is related to the PSGL1 level and influences the risk of atherosclerosis and coronary heart disease." (PMID 39857592, 2024). "SELPLG was identified to promote the progression of atherosclerosis via regulating the interaction of activated immune cells and endothelial cells and also elevating expression levels of TNF-α and IL6." (PMID 36430760, 2022). "Bioinformatics results of the study revealed that Selectin P Ligand (SELPLG) is one of the core crosstalk genes involved in the mechanisms between atherosclerosis and periodontitis." (PMID 36430760, 2022). "PCR-Array: mRNA expression of 16 of 84 atherosclerosis-related genes were significantly regulated at least 2-fold by IL-1α alone in comparison to control (p<.05), ranging from 8.3-fold (SELPLG) to 108.4-fold (TGFB2) up-regulation." (PMID 28323859, 2017).
myeloma (21 papers, 2015 to 2025). "We were surprised to find the three proteins that most-distinguished myeloma plasma cells from B-ALL, based on fold-change and p-value, were not canonical markers at all: gamma-glutamyl transferase 1 (GGT1), selectin-P ligand (SELPLG), and cell adhesion molecule 1 (CADM1)." (PMID 35840578, 2022).
COVID-19 (13 papers, 2020 to 2023). A disease caused by infection with severe acute respiratory syndrome coronavirus 2. "(a) UMAP representations of immune cell populations from healthy participants and COVID-19 patients annotated by cell types (left) and differential expressions of counter receptors ITGAL, SELPLG, and CX3CR1, which are known to interact with surface molecules of activated endothelial cells (right)." (PMID 33752798, 2021).
lung cancer (13 papers, 2017 to 2025). A malignant neoplasm involving the lung. "In summary, SMC6, CDC27, CDC7, RACGAP1, SMC4, NCF1,2,4, SELPLG and CFP are significantly associated with T2DM and lung cancer, making them potential target genes for disease prediction and treatment in the future." (PMID 38468345, 2024). "By analyzing PSGL-1 mRNA (SELPLG gene) expression in a published scRNA-seq dataset comprising tumor derived and peripheral immune populations from 7 patients with non–small cell lung cancer, we found SELPLG is broadly expressed across immune cell populations within the TME." (PMID 37819238, 2023).
melanoma (13 papers, 1997 to 2025). A malignant, usually aggressive tumor composed of atypical, neoplastic melanocytes. "Recently, it has been shown that SELPLG acts as an immune checkpoint regulator in colorectal cancer, head and neck squamous cell carcinoma, and melanoma, making it a potential novel therapeutic target for cancer." (PMID 38468345, 2024). "Expression of SELPLG (P selectin ligand) in the TME is correlated with increased melanoma infiltration by B cells, CD4+ and CD8+ T cells, DCs, and macrophages." (PMID 37435077, 2023).
glioma (11 papers, 2016 to 2025). A benign or malignant brain and spinal cord tumor that arises from glial cells (astrocytes, oligodendrocytes, ependymal cells). "Decreased SELPLG expression has been identified in recurrent compared to primary gliomas." (PMID 27096627, 2016).
colon carcinoma (8 papers, 2021 to 2025). "The results unraveled that CCL5, THBS, SPP1, ICAM, and TNF signaling pathways were more abundant in colon cancer (red), whereas SELPLG, LIGHT, CSF, and BAFF signaling pathways were more abundant in rectal cancer (green)." (PMID 37675100, 2023). "Among these, the SPP1 signaling pathway, a characteristic gene of the Ma1 subgroup, is highly active in colon cancer, whereas the SELPLG and LIGHT signaling pathways are highly active in rectal cancer." (PMID 37675100, 2023).
colorectal cancer (6 papers, 2022 to 2025). A primary or metastatic malignant neoplasm that affects the colon or rectum. "Moreover, SELPLG has been studied in several kinds of cancers as potential diagnostic or prognostic biomarkers, such as colorectal cancer (CRC), head and neck squamous cell carcinoma (HNSCC), anaplastic large T-cell lymphoma (ALCL), uveal melanoma, and so on." (PMID 35153625, 2022). "In a study of colorectal cancer specimens, lnc-SELPLG-2:1 expression was increased based on our findings." (PMID 36199080, 2022). "In colorectal cancer (CRC), it has been evidenced that SELPLG deficiency could render intestinal tissue more vulnerable to grow colorectal tumors." (PMID 35153625, 2022).
inflammatory skin disease (5 papers, 2016 to 2024). Inflammatory skin disorders covers a broad category that includes many conditions ranging in severity, from mild itching to grave medical health complications These disorders are common in people of all ages and races. "Likewise, several chemokines, CCL3L1, CCL17, CXCL2, and selectin SELPLG, were upregulated at week 8 in CS and have been implicated in various inflammatory skin diseases." (PMID 34925353, 2021).
Obesity (5 papers, 2018 to 2023). Accumulation of substantial excess body fat. "SELPLG is a gene with a role in immune cell trafficking during inflammation and has been associated with adiposity and obesity." (PMID 37543566, 2023).
prostate carcinoma (5 papers, 2009 to 2024). A carcinoma that arises from epithelial cells of the prostate gland. "For example, lymphoid enhancer-binding factor 1 (LEF1) was found in ALL, selectin P ligand (SELPLG) was found in AML, and Bax was found in prostate cancer." (PMID 19915715, 2009).
acute myeloid leukemia (4 papers, 2017 to 2024). Acute myeloid leukemia (AML) is a group of neoplasms arising from precursor cells committed to the myeloid cell-line differentiation. "It has been reported to mediate the development and chemotherapy resistance of acute myeloid leukemia (AML), and blocking the binding of SELPLG to E-selectin is probably a new target." (PMID 35153625, 2022).
pneumonia (4 papers, 2016 to 2023). An acute, acute and chronic, or chronic inflammation focally or diffusely affecting the lung parenchyma, caused by an infection in one or both of the lungs (by bacteria, viruses, fungi, or mycoplasma.). "The role of the SELPLG gene in cold adaptation can be associated with resistance to pneumonia and other infections." (PMID 29297313, 2017).
neuroblastoma (3 papers, 2017 to 2025). Neuroblastoma (NB) is the most common solid, extracranial childhood tumor. "Cytotoxicity against SK-N-BE neuroblastoma cells (challenged 24h in coculture) was comparable between L1CAM-CAR T cells with and without SELPLG deficiency." (PMID 41394860, 2025).
osteosarcoma (3 papers, 2022 to 2025). A usually aggressive malignant bone-forming mesenchymal neoplasm, predominantly affecting adolescents and young adults. "Our study provides insight into lnc-SELPLG-2:1 as a biomarker of osteosarcoma, which can be used for diagnostic and therapeutic purposes." (PMID 36199080, 2022). "As lncRNA may affect the expression of their neighboring genes positively or negatively, the gene SELPLG may be impacted, resulting in osteosarcoma processes associated with a poor prognosis." (PMID 36199080, 2022). "Therefore, it is confirmed that lnc-SELPLG-2:1 expression is upregulated and may be implicated in osteosarcoma patients." (PMID 36199080, 2022). "The relative intensity also indicated that the expression level of lnc-SELPLG-2:1 is higher in the tumorous tissues of osteosarcoma patients in phases IIA, IIB, and IVB." (PMID 36199080, 2022). "Co-transfection of pcDNA3.1-lnc-SELPLG-2:1 and hsa-miR-10a-5p mimics decreased cell proliferation, migration, and invasion ability, and increased apoptosis and hsa-miR-10a-5p reversed the osteosarcoma-promoting effect of lnc-SELPLG-2:1." (PMID 36199080, 2022). "In this study, lnc-SELPLG-2:1 was identified as a potential regulator of osteosarcoma processes, including cell proliferation, apoptosis, migration, and invasion." (PMID 36199080, 2022). "In order to determine which lncRNA was involved in osteosarcoma, lncRNAs including lnc-SELPLG-2:1, lnc-DDX47–3:1, lnc-ZNF77–165:3, lnc-SRSF2–9:2, lnc-SAMD11–1:1, and lnc-PPP1R9B-4:2 were detected by RT-qPCR to determine if their sequences were consistent with sequencing results." (PMID 36199080, 2022). "Therefore, we believe that lnc-SELPLG-2:1 regulates osteosarcoma by promoting the mRNA and protein expression of BTRC via the competitive binding of hsa-miR-10a-5p." (PMID 36199080, 2022). "Therefore, we hypothesized that lnc-SELPLG-2:1 may serve as an osteosarcoma tumor activator." (PMID 36199080, 2022).
T cell lymphoma (3 papers, 2021 to 2025). "The present investigation aims at evaluating the expression of SELPLG and its potential molecular interactions in T-cell lymphomas." (PMID 34204843, 2021).
acute respiratory distress syndrome (2 papers, 2022 to 2023). Progressive and life-threatening pulmonary distress in the absence of an underlying pulmonary condition, usually following major trauma or surgery. "For instance, SELPLG is identified as a novel acute respiratory distress syndrome (ARDS) susceptibility gene and a promising therapeutic target in ARDS." (PMID 35153625, 2022).
Hepatitis (2 papers, 2022 to 2024). Inflammation of the liver. "We found increased SELPLG expression in Hepatitis C-specific CD8+ T cells in patients with chronic infection, whereas these levels were decreased in patients that resolved the infection." (PMID 35774790, 2022).
Alzheimer disease (1 paper, 2022). A progressive, neurodegenerative disease characterized by loss of function and death of nerve cells in several areas of the brain leading to loss of cognitive function such as memory and language. "SELPLG gene that encodes P-selectin glycoprotein ligand 1 had the highest level of expression in blood across all tissues analyzed in GTEx and is upregulated in Alzheimer’s disease." (PMID 35313970, 2022).
chronic hepatitis C infection (1 paper, 2022). "We found that SELPLG expression was increased in virus-specific CD8+ T cells in patients with chronic hepatitis C infection, whereas levels decreased in patients that cleared the virus, indicating that PSGL-1 is part of the T exhaustion phenotype in patients." (PMID 35774790, 2022).
Hodgkins lymphoma (1 paper, 2021). A heterogeneous group of malignant lymphoid neoplasms of B-cell origin characterized histologically by the presence of Hodgkin and Reed-Sternberg (HRS) cells in the vast majority of cases. "Interestingly, classical Hodgkin lymphomas (CHLs) and T-cell/histiocyte-rich large B-cell lymphomas (THRLB-CLs) showed a high level of SELPLG expression." (PMID 34204843, 2021).
Pancreatic cancer (1 paper, 2020). "Pancreatic cancer cell-derived T-EVs containing active TFs and P-selectin glycoprotein ligand 1 (SELPLG) have been revealed to accumulate at locations of impairment, reducing haemorrhage upon injection into living mice." (PMID 33081785, 2020).
periodontitis (1 paper, 2022). An acute or chronic inflammatory process that affects the tissues that surround and support the teeth. "Nonetheless, it remains inconclusive whether periodontitis-triggered systemic inflammation can cause the upregulation of SELPLG." (PMID 36430760, 2022).
primary effusion lymphoma (1 paper, 2022). A large B-cell lymphoma located in the body cavities, characterized by pleural, peritoneal, and pericardial fluid lymphomatous effusions and that is always associated with human herpes virus-8 (HHV-8). "Whereas, SELPLG showed strong expression in primary effusion lymphoma (PEL), and it was vital for cell migration and chemotaxis, the expression of which was converse in OS in our research." (PMID 35153625, 2022).
tumor (114 papers, 2009 to 2026). "The endogenous PSGL-1 encoded by SELPLG would facilitate the recruitment of monocytes to metastasize tumor cells, then contributing to metastasis would result in decreased survival, which supported our findings indirectly." (PMID 35153625, 2022). "On day 14, the median luminescent signal of SELPLG-deficient L1CAM-CAR T cells was significantly stronger in the tumor compared to L1CAM-CAR T cells retaining endogenous SELPLG expression." (PMID 41394860, 2025). "Tumor-infiltrating L1CAM-CAR T cells expressed lower levels of the selectin P ligand (SELPLG) glycoprotein and higher levels of the T cell-specific adaptor protein, SH2D2A." (PMID 41394860, 2025). "The TISIDB results showed that SELPLG was related to the abundance of CD4+ T cells in tumor-infiltrating lymphocytes, while SELPLG and its receptor SELL were also closely related to the cellular abundance of activated DCs24." (PMID 35710862, 2022). "As confirmed by FISH, the level of lnc-SELPLG-2:1 was reduced in the tumor after treatment with sh-lnc-SELPLG-2:1, demonstrating that the sh-RNA was effective." (PMID 36199080, 2022). "In the B-cell setting, the highest SELPLG gene expression was pointed out in plasma cells and related neoplasms." (PMID 34204843, 2021). "Most recent findings define SELPLG as a T cell inhibitory receptor and demonstrate that eliminating or blocking SELPLG promotes tumor infiltration and the capacity for T cells to migrate in immunocompetent mouse tumor models." (PMID 41394860, 2025). "Given that the significant interference of SFT on cytoskeleton, we evaluated the directed impact of SFT on PSGL1, but the data showed that SFT had no significant inhibition on SELPLG (the encoding gene of PSGL1) mRNA in ICC‐TRCs or tumor tissues." (PMID 39605300, 2025). "To investigate how mTORC2 may regulate SELPLG/PSGL-1 expression in tumor cells, we found that MLST8-KO cells exhibited a significant decrease in expression of EPAS1, the gene encoding HIF2α which was previously shown to be regulated by mTORC2." (PMID 40640525, 2025). "In addition, P-selectin glycoprotein ligand-1 (PSGL-1, encoded by SELPLG), identified as an immune checkpoint in tumor immunity, inhibits T-cell proliferation, whereas Selplg-deficient T cells exhibit functional exhaustion." (PMID 40365538, 2025). "In this dataset, we consistently found SELPLG expression in a diverse array of human tumor types." (PMID 37819238, 2023). "Furthermore, given to the important role of selectins in tumor metastatic spread, the immune cell infiltration was also analyzed between high and low SELPLG expression OS patients." (PMID 35153625, 2022). "In order to confirm the functions of lnc-SELPLG-2:1 further, a tumor formation assay was conducted." (PMID 36199080, 2022). "Recently, the crucial role of SELPLG in tumor metastasis has been demonstrated." (PMID 35153625, 2022). "Among these molecules, CXCR4 and SELPLG play a key role in the tumor-tropic processes of MSCs." (PMID 35463812, 2022). "SELPLG-deficient T cells might, therefore, transit more freely into the tumor because they are not retained at vessel walls or stromal structures." (PMID 41394860, 2025). "SELPLG act a positive effect to enhances neutrophil recruitment and NET formation, its deficiency might affect neutrophil function and immune cell differentiation and therefore act on tumor growth." (PMID 35252353, 2022). "The key ligands involved in MSC homing include chemokine receptors CCR2, CXCL12, and CXCR4 and adhesion ligands, such as SELPLG and SELP, among which CXCR4 is one of the most important molecules mediating the tumor-homing effects of MSCs." (PMID 35463812, 2022). "For Fra-2 cl 2 primary tumours, genes such as SRGN (Serglycin) and ESAM were upregulated, while CD99 and SELPLG (selectin P ligand) were downregulated." (PMID 34693476, 2022).
tumor (continued). "In SELPLG-deficient tumor-infiltrating T cells, expression analysis of the same selected genes revealed that CCR7 and ITGAL were significantly upregulated in SELPLG-negative cells that infiltrated the tumor model." (PMID 41394860, 2025). "SELPLG-deficient L1CAM-CAR T cells were not more effective at limiting tumor growth or improving overall survival than L1CAM-CAR T cells retaining SELPLG expression." (PMID 41394860, 2025). "Taken together, our single-cell RNA expression analysis affirmed that SELPLG and SH2D2A are differentially regulated in single tumor-infiltrating L1CAM-CAR T cells, suggesting a functional role, while TIAM2, CORO1B and MYH10 do not seem to influence L1CAM-CAR T cell migration." (PMID 41394860, 2025). "We found that the CCL5-CCR1, SELPLG-SELL, CXCL10-CXCR3, and CXCL9-CXCR3 pathways might play important roles in the communication between the immune cells in tumor microenvironment." (PMID 35710862, 2022). "Because HIF2α plays an important role to regulate the expression of SELPLG/PSGL-1 and glycolytic enzymes downstream of mTORC2, it will be interesting to test if this inhibitor is also effective in inhibiting LUSC tumor growth and whether it can improve the current immunotherapy." (PMID 40640525, 2025). "Also, TGFB1, ENG, B2M, HLA-F, SELPLG, and ITGB2 were significantly increased in tumor-associated macrophages, compared with those nontumor-associated macrophages." (PMID 36249427, 2022). "Our findings verified that SELPLG knockout significantly improved L1CAM-CAR T cell migratory capacity in vitro, without altering anti-tumor function, and demonstrated that CAR T cells dynamically downregulate SELPLG surface expression during migration." (PMID 41394860, 2025). "SELPLG knockout benefited CAR T cell in vitro trans-endothelial migration, but did not enhance anti-tumor efficacy in an immunodeficient mouse model." (PMID 41394860, 2025). "Also, Tregs from NI ad I TDLN share CD58, ITGAM, MCAM, CEACAM4, SELPLG, and HMMR expression, which could ensure recirculation among TDNLs; and Tregs from I TDLN and tumor Tregs share ICAM1 expression, which could be responsible for the migration among tissues with presence of tumor cells." (PMID 32601304, 2020).